CTLA4 (cytotoxic T-lymphocyte associated protein 4)
Diseases named in the same sentence as CTLA4 in open-access papers (continued):
Sharing a sentence is not in itself a finding about the gene and the disease.
tumor (continued). "In addition, anti-CTLA-4 antibodies induce antibody-dependent cytotoxicity (ADCC) in tumor macrophages." (PMID 37860188, 2023). "Furthermore, in contrast to the lack of effect of ICIs in animals treated with RT alone, co-treatment with fulvestrant and RT reduced tumor size and prolonged survival in concert with the individual ICIs, anti-PD-L1 and anti-CTLA-4." (PMID 37312163, 2023). "This eventually masked the impact of immune escape in RE tumours, as expression of checkpoint molecules CD274 (PD-L1; programmed cell death ligand 1) and CD152 (CTLA-4; cytotoxic T-lymphocyte-associated protein 4) were found to be markedly increased at baseline levels." (PMID 37460712, 2023). "Genetic changes, such as homozygous or biallelic gene loss for B2M, lead not only to decreased HLA class I expression on tumour cells, but also increased resistance to immune checkpoint receptors targeting immunotherapy, e.g., anti-PD-1 and anti-CTLA-4 treatment." (PMID 36980527, 2023). "Tumor cells evade the body’s immune attack by enhancing the inhibitory signals of CTLA-4 and PD-1." (PMID 37240574, 2023). "Furthermore, immune checkpoints, including indoleamine 2,3 dioxygenase (IDO), cytotoxic T-lymphocyte-associated protein 4 (CTLA-4), and programmed cell death protein 1 (PD-1), have been shown to regulate tumor immune tolerance through autophagy pathways." (PMID 37270839, 2023). "Independent of PD-1, PD-L1, and CTLA4 expression, tumor mutation load (TMB) has been shown in recent years to be a valuable biomarker for predicting the response of PD-1/PD-L1 and CTLA4/B7-1 axis inhibitors in cancer patients treated with ICI." (PMID 38057871, 2023). "Furthermore, the combination immunotherapy of the vaccine and anti-CTLA-4 monoclonal antibody exhibited a significantly enhanced anti-tumor immune response compared to either the vaccine or monoclonal antibody alone." (PMID 37978542, 2023). "Therefore, the metabolism of the tumor and immune cells is controlled by the interaction between immunological checkpoints and their ligands, such as PD-1/PD-L1 and CTLA-4/CD86." (PMID 36677919, 2023). "Our data also suggest that PD-1-mediated cell intrinsic effects are distinct from that of CTLA-4, thus, blockade of both molecules might be of advantage to initate tumor rejection as well as longevity of the executing cells." (PMID 37205114, 2023). "Indeed, we found that tumor growth was significantly reduced in mice treated with combined IL-6– and CTLA‐4–blocking Abs compared with mice treated with isotype control Abs (P = 0.0001), single-agent CTLA-4 blockade (P = 0.0207), or IL-6 blockade (P = 0.0002)." (PMID 36881480, 2023). "Research has indicated that when immune checkpoint blockers (such as anti-ctLA-4 and/or anti-Pd-1) are used in combination with anticancer vaccines in immunotherapy, it can suppress tumor growth while also increasing the proportion of effector T cells that produce IFN-γ." (PMID 37941546, 2023). "Compared to the Treg cells in blood or adjacent normal tissue, Tregs in the tumor express higher levels of CTLA4, inducible T cell costimulator (ICOS) and tumor necrosis factor receptor superfamily member 9 (TNFRSF9; encoding 4-1BB), which reflect an activated state." (PMID 37187731, 2023). "Moreover, the innovative application of a bifunctional antibody, Y-trap, capable of targeting both TGFβ and CTLA-4, has also proven effective in mitigating immune tolerance and augmenting tumour-infiltrating lymphocytes." (PMID 37454231, 2023). "Monoclonal antibody targeting CTLA-4 can trigger an anti-tumor immune response." (PMID 36810098, 2023). "Oral supplementation with B. fragilis in germ-free mice restored the therapeutic response of anti-CTLA-4 via the induction of T helper 1 (TH1) immune responses in tumor-draining lymph nodes (LN) and the promotion of the maturation of intra-tumoral dendritic cells (DC)." (PMID 37298653, 2023).
tumor (continued). "These drugs work by targeting specific molecules such as programmed death-1 (PD-1) or its ligand programmed death ligand-1 (PD-L1) and cytotoxic T lymphocyte-associated antigen-4 (CTLA-4) to reestablish anti-tumor responses and prevent tumor cells from evading immune surveillance." (PMID 38026944, 2023). "Besides, the NP-based approach makes CTLA-4 blockades penetrate the tumor site and augment the immune system locally, reducing irAEs." (PMID 37735656, 2023). "combined CTLA-4 blocker with radiotherapy and found a significant reduction in tumour growth rate." (PMID 38259489, 2023). "Intratumoral injection of anti-CTLA4 antibodies in a slow-release formulation with an eight-fold lower dose of antibodies achieved tumor eradication as systemic delivery and resulted in thousand-fold decreased levels of antibodies in the serum, reducing adverse events and the risk of autoimmunity." (PMID 38006049, 2023). "Immune checkpoint inhibitors (CIs), such as anti-CTLA-4 and anti-PD-1 blocking antibodies, target the inhibitory receptors on T-cells, including programmed cell death protein-1 (PD-1) and cytotoxic T-lymphocyte-associated protein-4 (CTLA-4), with the goal of enhancing anti-tumor T-cell function." (PMID 37626741, 2023). "Antisense knockdown of CD47 can delay the growth of some cancers in immune-competent mice, but tumor ablation and increased long-term survival have been achieved only by combining with local tumor irradiation, cytotoxic chemotherapy, or anti-CTLA4 or anti-PD-1 ICI." (PMID 36768931, 2023). "CD8+ TEXs expressing CST7 instead of CTLA4 or PDCD1 was detected in tumour tissues." (PMID 36855810, 2023). "Cytotoxic T lymphocyte-associated antigen-4 (CTLA-4) and programmed cell death protein 1 (PD-1), two immune checkpoints that control lymphocyte activation and balance immune responses, can shield tumor cells from the immune system." (PMID 37251440, 2023). "Immune checkpoint proteins such as CTLA-4 or PD-1 contribute to declines in anti-tumor immunity." (PMID 37420216, 2023). "Besides, a combination of CTLA-4 with GM-CSF-expressing tumor cell vaccine can be therapeutically effective; it targets prominent regulatory pathways of the immune system and modifies the immune response." (PMID 37568193, 2023). "Furthermore, CCL2 in tumors and CCR2 on tumor-infiltrating monocytes were increased with combination anti-PD-1/CTLA-4 treatment." (PMID 37449205, 2023). "HNSC tumor tissues show elevated CTLA4 expression, which is related to OS." (PMID 38025757, 2023). "Nivo and the cytotoxic T-lymphocyte antigen-4 (CTLA-4)-specific antibody ipi have different mechanisms of action that contribute to the release of anti-tumor T-cells from checkpoint blockade and to the induction of de novo anti-tumor T-cell responses, respectively." (PMID 37009054, 2023). "Similarly, CT26 tumor–bearing animals treated with mANK-101 or systemic CTLA-4 blockade alone had 40% and 60% tumor-free survival rates respectively, while the combination had a 90% tumor-free survival rate." (PMID 38063196, 2023). "An Nb36/liposome complex was constructed and utilized as a blocker of the CTLA-4/B7 signal pathway in a combination with dendritic cell (DC)/tumor fusion vaccine to enhance the CD8+ T cell cytokine secretion, activation, proliferation, as well as specific cytotoxicity." (PMID 37419930, 2023). "Additionally, a phase I trial showed that combining GM-CSF with CTLA-4 blockade led to clinically significant anti-tumor responses in patients with metastatic, castration-resistant prostate cancer." (PMID 37929901, 2023). "High expression of PD-L1 and CTLA-4 inhibits tumour immunity and induces tumour immune escape." (PMID 37691922, 2023). "CTLA-4 (CD152) is a negative regulator of co-stimulation of CD28 that is required for the activation of an antitumor T cell in a lymph node upon recognition of its specific tumor antigen, which is presented by an APC." (PMID 37504333, 2023).
tumor (continued). "Immune checkpoint inhibitors (ICI) act on co-inhibitory receptors, such as CTLA-4 and PD-1, on immune system cells, or their ligands, such as PD-L1, on tumor and immune cells, in order to prevent the resistance of these cells to the immune system, potentiating the cytotoxic killing of tumor cells." (PMID 37296986, 2023). "Dual checkpoint blockade, which have synergistic anti-tumor effects in advanced malignancies, such as anti-CTLA-4 and anti-PD-1, could potentially serve as a more effective therapeutic strategy." (PMID 38111587, 2023). "Therefore, the addition of PD‐1 to CTLA‐4 has a synergistic effect on the activation of T cells and tumor‐restrain immune response." (PMID 36951654, 2023). "Given that PD-L1, PD-1, and CTLA-4 show a positive correlation with each other in tumor tissues, combining these drugs might show overlapping clinical applications." (PMID 36508191, 2023). "Cancer immunotherapy with immune checkpoint inhibitors (ICIs), including monoclonal antibodies (mAbs) against cytotoxic T lymphocyte-associated protein 4 (CTLA-4) and PD-1/PD-L1, rescues dysfunctional cytotoxic effector CD8+ T cells, leading to tumour regression." (PMID 36732592, 2023). "CTLA-4 signaling plays a greater role in preventing the commencement of T-cell response; while PD-1 plays a more significant role later on and serves to abstract T-cell activity in the immunological setting of tumor microenvironment." (PMID 37415164, 2023). "The tumor cell-extrinsic factors include inhibitory immune checkpoints (CTLA-4, PD1, and others), T cell exhaustion and phenotype change, immune suppressive cell populations (Tregs, MDSCs, and type II macrophages), and the release of cytokines and metabolites in the TME." (PMID 36765892, 2023). "This combination may include PD-1/PD-L1 antibodies to be used along with other immune checkpoint inhibitors (e.g., CTLA-4 antibodies), neoantigen tumor vaccines, antiviral drugs, anti-microbiome modulators, chemotherapy, and radiation therapy." (PMID 36829496, 2023). "Anti-CTLA-4 antibody alleviates T-cell inhibition, while local hyperthermia induces localized immune stimulation, prompting a stronger immune response against the tumor." (PMID 37860188, 2023). "In addition, nano-liposome C6-ceramide (LipC6) in combination with anti-CTLA4 antibody represents a novel therapeutic approach with significant potential in activating anti-tumor immune response." (PMID 36594091, 2023). "In addition, the splenocytes harvested from tumor-bearing mice were used to assay CTLA-4 and PD-1 expressions." (PMID 37764996, 2023). "PD-1-CTLA4 bsAbs could become useful in the NSCLC setting because of preferential binding to CTLA-4 on PD-1-activated dual-positive T cells in the tumor (limiting toxicities in normal organs)." (PMID 38067208, 2023). "Accordingly, a study in a CT26 tumor model showed that a triple blockade of VISTA/PD-1/CTLA-4 could improve the efficacy of PD-1/CTLA-4 dual blockade by promoting antigen-presentation in myeloid cells and reducing the quiescent state of CTLs." (PMID 37928556, 2023). "KRAS overexpression may be one general mechanism by which tumour cells upregulate the expression of the immune checkpoint regulator CTLA-4, thereby evading immune surveillance." (PMID 36902476, 2023). "Similarly, MEDI5752, which is a monovalent anti-PD-1/CTLA-4 BiSpecific, is currently under evaluation in patients and durable responses have been seen across diverse tumour types." (PMID 36936963, 2023). "Importantly, USP5 inhibition in combination with the MEK inhibitor, Trametinib, or anti-CTLA-4 antibodies has an additive effect on suppressing tumor growth in mice." (PMID 37208329, 2023). "In particular, it has been demonstrated that the MPAK pathway may control PD-L1 and CTLA-4 expression but may also impact on the tumor microenvironment (TME), promoting an immunosuppressive stroma through the secretion of cytokines and growth factors." (PMID 37958363, 2023).
tumor (continued). "However, tumour-infiltrating Tregs present in the tumour microenvironment, especially those expressing CTLA-4, intercept dendritic cells and render them tolerogenic and anti-inflammatory, which eventually stimulates T cell exhaustion instead of activation." (PMID 36319895, 2023). "Studies showed that blocking the CTLA-4 immune check points could activate the T-cells and reduce the immune-suppressive nature of T-cells in the tumor micro-environment." (PMID 37765317, 2023). "Upon the treatment of CD73-knockout mice with the combination with anti-CTLA-4 plus anti-PD-1, the tumor burden was significantly alleviated and survival was improved, along with the elevated ratio of the granzyme B+ effector CD8 T cells to the CD206+ macrophages in the TME." (PMID 37731483, 2023). "Interestingly, substantial increases in immune checkpoint therapy targets such as PD-L1 + tumor cells, PD-L1 + Tregs, and CTLA-4 + Tregs were found." (PMID 36058988, 2023). "Increased expression and binding of CTLA-4 to CD28 contributes to the activation of intracellular mechanisms responsible for the immunosuppression of the cytotoxic tumour cell killing reaction by CD8+ cytotoxic cells (CTLs) and the immunotolerance of tumour neoantigens." (PMID 36980527, 2023). "It remains to be determined whether inhibition of additional immune checkpoints such as CTLA-4 can produce antitumor responses by activating tumor-reactive effector T cells within the inflamed microenvironment of RMC tissues." (PMID 37568622, 2023). "However, for some tumors, such as melanoma, the treatment response rate was less than half, suggesting that the immune escape of tumor cells depends not only on immune checkpoints, such as CTLA-4 and PD-1/PD-L1 but also other immunosuppressive modalities." (PMID 37372117, 2023). "IFN-γ induces the expression of CTLA-4 and PD-L1 in tumor cells." (PMID 37370399, 2023). "Importantly, VISTA blockade has also demonstrated a combinatorial effect combined with CTLA-4 blockade to induce tumor regression in a murine model of SCC." (PMID 37795437, 2023). "CTLA-4 inhibitors are likely to restore anti-tumor immunity and exert anti-tumor effects." (PMID 38187388, 2023). "Inhibiting immune checkpoints by impeding the CTLA-4 or PD-1/PD-L1 axis could therefore reduce the immune escaping of tumor cells and represent a potential immunotherapeutic approach." (PMID 37415164, 2023). "Furthermore, the combination of the GNP-LO91-99 nanovaccine and anti-PD-1 or anti-CTLA-4 antibodies can reduce immune checkpoint expression and increase tumour sensitivity to the vaccine." (PMID 37514054, 2023). "However, through the application of antibodies that block negative feedback mechanisms—such as anti‐PD‐1, anti‐PD‐L1 and anti‐CTLA4—it's possible to induce tumour antigen‐specific immune responses and ultimately, eradicate the tumours." (PMID 37556076, 2023). "Again, combining CTLA-4 therapeutic inhibition with cancer vaccines may provide effective anti-tumor immunity through the efficient induction of immune response against low immunogenic tumor cells." (PMID 36109471, 2023). "Upregulation of CD80 may interact with cytotoxic T lymphocyte antigen 4 (CTLA4) to promote tumor progression and provide a potential target for biological antitumor therapy." (PMID 36892747, 2023). "In addition, IFNγ also increases the expression of checkpoint inhibitors, such as indoleamine-2,3-dioxygenase 1 (IDO1) and CTLA-4, leading to enhanced tumor growth." (PMID 37190141, 2023). "CTLA-4 modulates T cell activation during the first phase of immunological activation, while PD-1 is activated throughout the immune effector phase and is abundantly produced when tumor antigens are presented." (PMID 37405952, 2023). "Currently, most methods for detecting CTLA4 based on biopsy samples are invasive, due to the spatiotemporal heterogeneity of tumors, it is difficult for a single local tissue detection result to represent all tumor tissues well." (PMID 37798374, 2023).
tumor (continued). "Programmed cell death-1 (PD-1), cytotoxic T-lymphocyte-associated protein 4 (CTLA-4), and programmed cell death ligand 1 (PD-L1) are examples of inhibitory immune checkpoint molecules (ICMs) that suppress immune responses and allow tumor immune escape." (PMID 37251372, 2023). "The low abundance of CD8+ lymphocytes in tumor samples may be due to immune checkpoint inhibition as indicated by the high expression of PD-1, PD-L2, and CTLA4." (PMID 37298307, 2023). "Several studies have found that ICIs (including PD-1/PD-L1/CTLA4/LAG3) have an important function in maintaining tumor antigen tolerance but are usually hijacked by tumors to mediate their immune escape, leading to poor therapeutic outcomes in some patients with ICI therapy." (PMID 37047824, 2023). "Moreover, synergistic anti-tumor efficacy and effector memory T cell upregulation were also observed for the combination with anti-CTLA-4 antibody." (PMID 36793737, 2023). "CD44 participates in the immune escape of tumor cells may be achieved by affecting CTLA-4 on T cells." (PMID 37316699, 2023). "CTLA-4 can also reduce the adhesion ability of T cells by down-regulating the expression of adhesionmolecules, making T cells more difficult to infiltrate into the tumor microenvironment." (PMID 37322434, 2023). "CTLA-4 inhibitors can increase infiltrating T-cell in tumor, while PD-1/PD-L1 inhibitors cannot." (PMID 38283359, 2023). "Indeed, antibodies targeting CTLA-4 or TIM-3 have been shown to be effective in various mouse tumour models when administered early (day 3 post-inoculation) but are largely ineffective against established tumours (day 11 post-inoculation)." (PMID 37153625, 2023). "Recent studies to define characteristics of sarcomas which predict response or resistance to immunotherapy have included those examining tumor mutational burden, the tumor microenvironment (TME), and tumoral expression of immune checkpoint proteins PD-1, PD-L1, BTLA-4, CTLA4, and LAG3." (PMID 36826126, 2023). "Immune checkpoint inhibitor therapy has shown excellent efficacy for tumor treatment; nonetheless, recent studies have shown that programmed cell death protein 1 (PD1) and cytotoxic T lymphocyte-associated antigen-4 (CTLA4) blockades for the treatment of metastatic UM are ineffective." (PMID 37359513, 2023). "It’s worth noting that blocking the adenosine/adenosine receptor pathway combined with immune checkpoint inhibitors such as anti-PD-1 or anti-CTLA-4 can significantly enhance the efficacy of anti-PD-1 or anti-CTLA-4, including in anti-PD-1-/anti-PD-L1-tolerant tumor types." (PMID 37834375, 2023). "Hence, our findings demonstrated that the plant-produced anti-CTLA-4 2C8 mAb elicited strong antitumor responses and established similar degree of tumor growth inhibition with the commercially available anti-CTLA-4 drug." (PMID 37711295, 2023). "Besides, Axitinib cooperated with PD1 or CTLA4 blockade to reduce tumor burden and improve survival." (PMID 37398660, 2023). "Moreover, it has been largely demonstrated that CTLA-4 blockade results in enhanced immune responses as well as improved anti-tumor activity." (PMID 37180141, 2023). "Targeting Tregs using anti‐CTLA4 antibody combined with M1 oncolytic viruses induced tumor suppression and lymphocytotoxicity via decreasing Tregs and increasing the infiltration of CD45+ immune cells CD4+ or CD8+ T cells, releasing IFN‐γ, perforin, and granzyme." (PMID 36618103, 2023). "In the study of immune checkpoint correlation, we discovered that BASP1 expression was positively linked with a number of immunological checkpoints, such as PD‐1, PD‐L1, and CTLA‐4, which may increase the occurrence of immune escape from tumor cells." (PMID 37243901, 2023). "These tumor cells and infiltrates promote the production of chemokines, growth factors, and cytokines, which decrease antitumor activity due to immune checkpoint pathways like CTLA-4 and PD-1." (PMID 38006053, 2023).